FABP3 (fatty acid binding protein 3)
Diseases named in the same sentence as FABP3 in open-access papers (continued):
Sharing a sentence is not in itself a finding about the gene and the disease.
neurodegenerative disease (7 papers, 2019 to 2025). A disorder of the central nervous system characterized by gradual and progressive loss of neural tissue and neurologic function. "However, previous related studies have reported associations between neurodegenerative diseases and some specific genes (e.g., FABP3 and ApoE4)." (PMID 36983769, 2023). "It is therefore likely that the elevated FABP3 levels that we observe in microglia reflect a response to the lipid burden that microglia are facing in diseased conditions specifically upon GRN deficiency but also in other neurodegenerative diseases." (PMID 37775827, 2023). "The top-ranking transcripts ranked by Manhattan distance included CHCHD2 (also known as MNRR1) and Clusterin (CLU) upregulation, with downregulation of FABP3 and S100A4, modulation, all having previously been associated with neurodegenerative disease;." (PMID 41173878, 2025). "Notably, FABP3 has been identified as a potential biomarker for neurodegenerative diseases and is suggested to play a role in cardiac development." (PMID 39824970, 2025). "It is worth noting, that a valuable feature of the biomarker is not only detecting in the early stages of the disease but also useful in differentiation with other neurodegenerative diseases, which could be pivotal in the case of FABP3 protein." (PMID 34300173, 2021).
infection (4 papers, 2020 to 2023). The state of being infected such as from the introduction of a foreign agent such as serum, vaccine, antigenic substance or organism. "The number of tyrosine hydroxylase (TH)- and phosphorylated α-Syn (Ser-129)-positive cells following α-Syn PFF injection significantly decreased in Fabp3−/− mice and markedly increased by AAV-GFP/FABP3 infection." (PMID 32210174, 2020).
myopathy (1 paper, 2024). A disease of the muscle in which the muscle fibers do not function properly. "The main finding of our investigation from a clinical perspective is that this secondary CoQ10 deficiency is not correlated with FABP3 level, a sensitive and specific biomarker of myopathy." (PMID 39795963, 2024). "Our main hypothesis was that high-intensity statin treatment of statin-naïve early-onset STEMI patients decreased serum CoQ10 levels and this secondary CoQ10 deficiency was correlated with an increased level of fatty acid-binding protein-3 (FABP3), a sensitive and specific biomarker of myopathy." (PMID 39795963, 2024). "Our results show that FABP3 levels significantly decreased and reached values reported by healthy controls or that of stable diabetic patients with normal ejection fraction, which is reassuring and suggests that CoQ10 depletion did not lead to significant myopathy." (PMID 39795963, 2024).
FABP3 also shares sentences with these, for which no sentence is quoted: acute myocardial infarction (29 papers); chronic kidney disease (8); pulmonary embolism (8); cardiomyopathies (6); diabetic nephropathy (5); injury (5); renal failure (5); malaria (3); myocarditis (3); prediabetes (3); unstable angina (3); acute cholecystitis (2); autism spectrum disorder (2); Brain atrophy (2); brain tumor (2); colorectal cancer (2); dengue (2); depression (2); falciparum malaria (2); glomerulopathy (2); hyperglycaemia (2); infarction (2); intracerebral hemorrhage (2); kidney disease (2); lymph node metastasis (2); multiple sclerosis (2); Myocardial necrosis (2); neurological disease (2); Parkinson’s (2); pneumonia (2).
A further 79 diseases each share a sentence with FABP3 in 2 papers or fewer.